CLEC5A (C-type lectin domain containing 5A)
Diseases named in the same sentence as CLEC5A in open-access papers (continued):
Sharing a sentence is not in itself a finding about the gene and the disease.
ZIKV infection (2 papers, 2019 to 2023). "Overall, our results show that CLEC5A deficiency ameliorated the decline of testicular function and sperm count which are clinical features of ZIKV infection." (PMID 36803804, 2023). "Combined, these data support the idea that CLEC5A may be a pivotal mediator of testicular damage, and that it may be associated with the oligospermia and spermatid malfunction resulting from ZIKV infection." (PMID 36803804, 2023). "This suggests that CLEC5A plays a role in the pathogenic effects of ZIKV infection." (PMID 36803804, 2023). "In conclusion, our ZIKV infection mouse model shows for the first time that CLEC5A exacerbates ZIKV infectivity." (PMID 36803804, 2023). "This agrees with previous work showing that CLEC5A knockdown decreased the viral load in adult human monocytes post-ZIKV infection." (PMID 36803804, 2023). "We next assessed whether ZIKV infection of the testicular tissues is affected by the functional presence of CLEC5A which is abundant in testicular tissues." (PMID 36803804, 2023). "This suggests that ZIKV infection triggers a CLEC5A-involved testicular injury." (PMID 36803804, 2023). "In addition, the partial rescue of spermatid counts and motility under ZIKV infection by clec5a knockout implicate CLEC5A as a potential target for therapies to treat ZIKV-infection-induced orchitis." (PMID 36803804, 2023). "However, the role of CLEC5A in ZIKV infection has thus far remained obscure." (PMID 36803804, 2023). "Cell surface molecules of potential importance for ZIKV infection include the C-type lectin receptors CD209 (DC-SIGN), CLEC5a and mannose receptor (MR) and the phosphatidyl serine receptors T-cell immunoglobulin and mucin domain (TIM)-1 and TAM receptors Tyro3 and AXL42–45." (PMID 31289325, 2019). "To investigate whether CLEC5A affects the functionality of ZIKV-infected testes, we assessed whether the level of testosterone, which is important for spermatogenesis, was affected by ZIKV infection." (PMID 36803804, 2023).
Acute hepatitis (1 paper, 2021). Acute hepatic injury resulting from inflammation typically accompanied by increased serum alanine transaminase activity. "Even though the nature of CLEC5A endogenous ligands is not been characterized yet, CLEC5A-deficient mice are resistant to collagen-induced autoimmune arthritis and concanavalin A-induced acute hepatitis." (PMID 34116654, 2021).
anaplastic astrocytoma (1 paper, 2022). "In GBM, CLEC5A was higher than that in astrocytoma and anaplastic astrocytoma, accompanied by an increase in M2-type macrophage infiltration." (PMID 35979347, 2022).
Anxiety (1 paper, 2024). Intense feelings of nervousness, tension, or panic often arise in response to interpersonal stresses. "In addition, we examined whether the Clec5a knockout affects locomotor and anxiety-like behaviors by the open field and elevated plus maze tests." (PMID 39443966, 2024). "Therefore, deleting Clec5a did not alter locomotor activity, but its impact on anxiety-related behaviors requires further investigation." (PMID 39443966, 2024).
brain glioblastoma (1 paper, 2019). A WHO grade IV malignant astrocytic tumor that arises from the brain, usually the cerebral hemispheres. "To determine whether CLEC5A mRNA expression is altered or co‐expressed in brain glioblastoma tissues, we searched multiple databases to compare CLEC5A expression levels involving brain tumour tissues and controls." (PMID 30834619, 2019). "TCGA (n = 552) and Sun Brain (n = 104) (data not shown) were selected to analyse CLEC5A mRNA expression in brain glioblastoma tissues." (PMID 30834619, 2019).
Cognitive impairment (1 paper, 2024). Abnormal cognition is characterized by deficits in thinking, reasoning, or remembering. "Therefore, CLEC5A deficiency enhances microglial recruitment and phagocytosis, resulting in decreased plaque burden and ameliorated cognitive deficits." (PMID 39443966, 2024). "Therefore, inhibiting CLEC5A may be a potential approach to alleviate the Aβ-induced cognitive impairments." (PMID 39443966, 2024).
cutaneous skin melanoma (1 paper, 2022). "The results exhibited that the CLEC5A mRNA expression was mainly negatively correlated with its DNA methylation in most tumors but only positively correlated with its DNA methylation in only some tumors, such as SKCM (cutaneous skin melanoma), TGCT (testicular germ cell tumors), LIHC and HNSC." (PMID 35979347, 2022).
Dengue hemorrhagic fever (1 paper, 2014). A serious condition caused by Dengue virus infection. "Blockade of CLEC5A/MDL-1, a C-type lectin critical for dengue hemorrhagic fever and Japanese encephalitis virus infection, inhibits NLRP3 inflammasome activation and pyrotopsis in GM-M." (PMID 25324778, 2014).
diabetic neuropathy (1 paper, 2021). A chronic, pathological complication associated with diabetes mellitus, where nerve damages are incurred due to diabetic microvascular injury involving small blood vessels that supply these nerves, resulting in peripheral and/or autonomic nerve dysfunction. "Taken together, the results indicate that intraneuronal ATF3, but not CLEC5A, mediates the induction of ER stress and neuroinflammation associated with diabetic neuropathy." (PMID 34172832, 2021).
endotoxemia (1 paper, 2024). "In the present study, we found that probiotic supplementation increased CLEC5A expression 3 h post-prandial and may explain the reduced dietary endotoxemia we have previously reported." (PMID 39457699, 2024).
fracture (1 paper, 2025). "Finally, CLEC5A was one of the proteins with the strongest associations with hip fracture, any fracture, and BMD." (PMID 39919333, 2025).
Hepatitis (1 paper, 2024). Inflammation of the liver. "The Clec5a level was dramatically elevated in the mouse brain after JEV infection, and the ratio of CLEC5A+ cells was increased in the liver of the hepatitis mouse model." (PMID 39443966, 2024).
hip fracture (1 paper, 2025). Traumatic or pathological injury to the hip in which the continuity of either the femoral head, femoral neck, intertrochanteric or subtrochanteric regions is broken. "Further, CLEC5A was one of the proteins with the strongest associations with hip fracture, but MR results did not suggest a causal effect on fracture risk." (PMID 39919333, 2025).
Hyperglycemia (1 paper, 2021). An increased concentration of glucose in the blood. "However, the DN, atf3−/−, and clec5a−/− mice exhibited similar hyperglycemia and body weight loss compared with the mice in the citrate and hypoDN groups." (PMID 34172832, 2021).
ischemia (1 paper, 2021). A hypoperfusion of the BLOOD through an organ or tissue caused by a PATHOLOGIC CONSTRICTION or obstruction of its BLOOD VESSELS, or an absence of BLOOD CIRCULATION. "The main finding is that 10 genes (Clec5a, CD14, Fgr, Hck, Anxa1, Lgals3, Irf1, Lbp, Ptx3, Serping1) may represent key molecular links underlying acute activation of immune cells in the hippocampus in response to experimental ischemia." (PMID 34944656, 2021).
laryngeal squamous cell carcinoma (1 paper, 2022). A squamous cell carcinoma that arises from the larynx. "CLEC5A expression was significantly higher in LSCC (laryngeal squamous cell carcinoma), PTC (papillary thyroid carcinoma) and UUC (ureteral urothelial carcinoma)than in para-cancer tissues, and was positively correlated with the infiltration proportion of macrophages." (PMID 35979347, 2022).
oligospermia (1 paper, 2023). Decreased number of spermatozoa in the semen. "CLEC5A, a myeloid pattern recognition receptor, therefore appears involved in the pathogenesis of ZIKV-induced orchitis and oligospermia." (PMID 36803804, 2023).
orchitis (1 paper, 2023). Inflammation of one or both testes due to viral or bacterial infections. "This ZIKV-induced testicular pathology was attenuated by CLEC5A deficiency, suggesting that targeting CLEC5A has potential as a therapeutic strategy for improving ZIKV-induced orchitis and associated illness." (PMID 36803804, 2023).
ovarian serous adenocarcinoma (1 paper, 2022). An adenocarcinoma that arises from the ovary and is characterized by the presence of malignant epithelial cells that, in well differentiated tumors, resemble the epithelium of the fallopian tube or, in poorly differentiated tumors, show anaplastic features and marked nuclear atypia. "Compared with OSC (ovarian serous adenocarcinoma), CLEC5A expression was higher in OSPC (ovarian serous papillary adenocarcinoma) and was significantly correlated with the increased infiltration of macrophages, M2-type macrophages, and T cell." (PMID 35979347, 2022).
pneumonia (1 paper, 2022). An acute, acute and chronic, or chronic inflammation focally or diffusely affecting the lung parenchyma, caused by an infection in one or both of the lungs (by bacteria, viruses, fungi, or mycoplasma.). "Thus, CLEC5A is a promising therapeutic target to reduce ventilator-associated lung injury and fibrosis in P. aeruginosa–induced pneumonia." (PMID 36048544, 2022).
prostate adenocarcinoma (1 paper, 2022). "In PRAD (prostate adenocarcinoma) tissues, CLEC5A expression was increased to accompany the increase of the Gleason score and the infiltration of macrophages, M2-type macrophages, and T cells also increased." (PMID 35979347, 2022). "The results indicated that CLEC5A methylation was significantly down-regulated in UCEC, LIHC, KIRC, KIRP (kidney renal papillary cell carcinoma), LUAD, HNSC, BRCA, BLCA, and PRAD (prostate adenocarcinoma)." (PMID 35979347, 2022).
scrub typhus (1 paper, 2022). Scrub typhus is a rare dust mite-borne infectious disease caused by the Orientia tsutsugamushi bacterium and characterized clinically by an eruptive fever which is potentially serious. "Future investigation with targeted blockage of Syk, Mincle, or Clec5a in the host will help define the immunologic impact of CLR cooperation on scrub typhus." (PMID 36678402, 2022).
septic shock (1 paper, 2023). Shock caused by infection; frequently caused by gram negative bacteria, although some cases have been caused by other bacteria, viruses, fungi, and protozoa; characterized by fever, chills, tachycardia, tachypnea, and hypotension. "CD177, CLEC5A, CYSTM1, MCEMP1, MMP8, and RGL4 were identified as hub genes, which were of considerable value in the early diagnosis of septic shock patients." (PMID 37359526, 2023). "In addition, higher expression levels of CD177, CLEC5A, CYSTM1, MCEMP1, MMP8, and RGL4 messenger RNA (mRNA) were observed in peripheral blood mononuclear cells (PBMCs) isolated from septic shock patients than from healthy donors." (PMID 37359526, 2023).
swine influenza (1 paper, 2019). An acute viral respiratory infection caused by a strain of influenza virus which is endemic in swine (pigs). "The CLEC5A gene also from the same region of Chr 4 has been associated with diseases (increased level of swine influenza) in pigs." (PMID 30988672, 2019).
tuberculosis (1 paper, 2017). A chronic, recurrent infection caused by the bacterium Mycobacterium tuberculosis. "Both Clec4d and Clec5a are of high relevance as they contribute to the recognition of tuberculosis and dengue virus respectively." (PMID 29213115, 2017).
infection (24 papers, 2011 to 2025). The state of being infected such as from the introduction of a foreign agent such as serum, vaccine, antigenic substance or organism. "Infection of bone marrow-derived macrophages from CLEC5A-deficient mice showed reduced levels of tumor necrosis factor alpha (TNF-α) and IP-10 but elevated alpha interferon (IFN-α) compared to those of wild-type mice." (PMID 27795434, 2017). "Consistent with results from RAW264.7 cells, infection of human primary monocytes with the DENV also caused upregulation of CLEC5A (bottom, S3)." (PMID 27561946, 2016). "Tyrobp (DAP-12 adapter) and its related receptors Trem2 and Clec5a are consistently up-regulated, while signaling genes have a mixed response in terms of association with infection, with about half of these genes being up-regulated." (PMID 27058578, 2016). "As vector- mediated transmission of virus is crucial for initial host infection, we investigated potential interactions between the CLEC5A and ZIKV." (PMID 36803804, 2023). "We found BAY treatment significantly reduced Mincle and Clec5a expression during infection at much lower concentrations than PIC or R406." (PMID 36678402, 2022). "MΦs can sense the bacterium via Syk-dependent receptors, including Mincle, Clec5a, and potentially others, at the initial stages of infection." (PMID 36678402, 2022). "These inflammatory cytokines have been previously reported to be upregulated during infection, for instance, upon CLEC5A-mediated interaction with DV." (PMID 35252461, 2022). "We found that Mincle/Clec4a and Clec5a transcription was significantly abrogated upon Syk inhibition at 6 h of infection." (PMID 36678402, 2022). "We also observed a significant increase (p < 0.05) in Clec5a transcripts during infection, which was almost completely abrogated in the presence of 1.0 μM BAY (79% reduction) and 50 μM PIC (97% reduction), respectively." (PMID 36678402, 2022). "While lung volume was reduced in Clec5a–/– mice after infection, it was much higher than in WT mice." (PMID 36048544, 2022). "Using primary murine MΦ, we revealed that Mincle and Clec5a are highly transcribed and Syk-dependent during infection." (PMID 36678402, 2022). "Examination and quantitation of NET formation revealed that L. monocytogenes induced NET formation 3 h post infection, and that this was almost completely abolished by blockade of CLEC5A." (PMID 28824166, 2017). "We found that bacterial load in the liver was dramatically elevated in Clec5a−/−Tlr2−/− mice at days 3 and 5 post-infection with L. monocytogenes." (PMID 28824166, 2017). "In contrast, luminescence intensity was still increasing at 4 h post-infection in the livers of WT/DNase I and Clec5a−/− mice and this correlated with bacterial loads in the liver and blood at the 4 h time point." (PMID 28824166, 2017). "The reduction of proinflammatory cytokine secreted by CLEC5A-expressing monocytes/macrophages recruits lower numbers of NK, B, and T cells to the site of infection, which likely lead to reduced lung damage and eventually increased mouse survival." (PMID 27795434, 2017). "Overall, the results suggest that CLEC5A mediates enhanced inflammatory responses in M-Mφ and GM-Mφ after infection with the recombinant H5N1 or H1N1 influenza viruss." (PMID 27795434, 2017). "While bacterial load increased gradually in Tlr2−/− mice, it was significantly elevated in WT/DNase I, and Clec5a−/− mice at day 3 post-infection." (PMID 28824166, 2017). "As observed in the CLEC5A− human M-Mφ, reduced levels of TNF-α and IP-10 (P = 0.063 and P = 0.046, respectively) were detected in BMM of CLEC5A−/− mice compared to those in the WT mice after infection." (PMID 27795434, 2017). "Increased CTX-1 level (from 1.4 ± 0.17 to 2.59 ± 1.1 ng/ml) was observed after DV infection, while anti-CLEC5A mAb reduced CTX-1 release from bone slice (0.39 ± 0.24 ng/ml)." (PMID 27033255, 2016).
infection (continued). "The elevated levels of TNF‐α during infection were associated with DAP12 activation, suggesting that CLEC5A directly interacts with the Dengue virion." (PMID 24330199, 2014). "Previously, MR and CLEC5A have been shown to bind Dengue virus in vitro leading to infection of macrophages and inflammasome activation respectively." (PMID 24330199, 2014). "Furthermore, CLEC5A can be considered as an innate immune checkpoint that amplifies pro-inflammatory signals to facilitate the occurrence of infection or sterile inflammation." (PMID 38028617, 2023). "Previous studies reveal the role of CLEC5A in infection and inflammation diseases." (PMID 35979347, 2022). "At day 5 post-infection, severe thickening of alveolar cell wall and cell infiltration were noted in WT mice (upper middle), while these phenomena were attenuated in clec5a−/−tlr2−/− mice after SARS-CoV-2 infection (upper right)." (PMID 35820906, 2022). "Altogether, CLEC5A may be considered as an innate immune checkpoint capable to amplify proinflammatory signals, and this way contributes to infection or to aseptic inflammation." (PMID 35252461, 2022). "CLEC5A-mediated infection is also responsible for the influx of cytokines into the CNS." (PMID 36560690, 2022). "Moreover, Clec5a−/− mice were more sensitive than Tlr2−/− animals to infection with a sub-lethal dose of L. monocytogenes." (PMID 28824166, 2017). "However, the presented data from this study has not excluded the possibility that Syk activation is also mediated by CLEC5A even under the intrinsic ADE infection." (PMID 25412261, 2014). "In contrast, administration of anti-CLEC5A mAb from day 0 (150 μg/mouse on days 0, 2, 4, 6, and 8) protected mice from early lethality (80% survival), and ∼50% mice survived for at least 16 days post infection." (PMID 22536153, 2012). "All the peripheral blood cells were labeled with CFSE at day 5 post infection whether treated with isotype or anti-CLEC5A mAb." (PMID 22536153, 2012). "This may be attributed the fact that the anti-CLEC5A mAb can enter the CNS when the permeability of BBB is increased during the acute stage of infection, where intracranial anti-CLEC5A mAb can inhibit microglia activation and attenuate neuroinflammation." (PMID 22536153, 2012). "Investigation of the ability of anti-CLEC5A mAb to protect Stat1−/− mice from JEV-induced lethality revealed that 50% of Stat1−/− mice that succumbed to JEV infection died in the early stages (6 days post infection), and all the mice died within 9 days post infection." (PMID 22536153, 2012). "There is no other study concerning CLEC5a and microbial recognition; however, when considered in the context of the previously discussed receptors, it is tempting to speculate that future work could reveal an involvement of CLEC5a in other types of infection and in triggering adaptive immunity." (PMID 21334257, 2011). "In agreement with this notion, we observed dose-dependent decreases in Mincle and Clec5a transcription when Syk was inhibited with BAY and PIC during infection." (PMID 36678402, 2022). "After infection with the VNHA,NA virus, the CLEC5A− and CLEC5A+ cells showed comparable M gene copies, suggesting that CLEC5A does not affect viral entry or replication in M-Mφ or GM-Mφ." (PMID 27795434, 2017). "Minimal induction of cytokines was observed in CLEC5A− and CLEC5A+ M-Mφ after infection with the UV-VNHA,NA virus." (PMID 27795434, 2017). "Overall, BMM derived from CLEC5A−/− mice showed reduced TNF-α and IP-10 but increased IFN-α compared to the WT mice after infection with the VNHA,NA virus or treatment with PIC." (PMID 27795434, 2017). "Cells were preincubated with anti-CLEC5A mAb for 1 h, followed by incubation with JEV at 37°C for 1 h, and supernatants were harvested to determine cytokine release at 24 h post-infection." (PMID 22536153, 2012).